RPS15AP1 (ribosomal protein S15a pseudogene 1)
Synonyms: dJ872K7.6; RPS15A_24_1692
Gene: Processed pseudogene on chromosome 20 (21,166,206 to 21,166,596, reverse strand). Ensembl gene ENSG00000214535.
Diseases named in the same sentence as RPS15AP1 in open-access papers:
RPS15AP1 is named in the same sentence as 2 diseases in open-access papers, as found by Europe PMC text mining. Sharing a sentence is not in itself a finding about the gene and the disease.
RPS15AP1 shares sentences with these, for which no sentence is quoted: autism (1 paper); schizophrenia (1).